COL22A1 (collagen type XXII alpha 1 chain)
Diseases named in the same sentence as COL22A1 in open-access papers:
COL22A1 is named in the same sentence as 43 diseases in open-access papers, as found by Europe PMC text mining. Sharing a sentence is not in itself a finding about the gene and the disease. The quoted sentences say what the papers report.
head and neck cancer (4 papers, 2016 to 2025). A primary or metastatic malignant neoplasm affecting the head and neck. "COL22A1 overexpression is linked to lymph node metastasis, pathological stage, and a poor patient outcome in the case of head and neck cancer." (PMID 40438725, 2025). "COL22A1 upregulation has been linked to prognosis in head and neck cancers." (PMID 27716027, 2016). "High expression of COL22A1 was observed in head and neck cancer, and was correlated with a decrease in disease-free survival." (PMID 36189307, 2022). "In head and neck cancer, highly expressed COL22A1 mRNA is statistically correlated with reduced disease-free survival and is significantly associated with lymph node metastasis." (PMID 32596344, 2020).
intracranial aneurysms (4 papers, 2018 to 2023). "While little is known about the function of COL22A1,currently unpublished results suggest it is important for maintaining vascularintegrity and mutations cause intracranial aneurysms." (PMID 28627999, 2018). "It has been established that COL22A1 maintains vascular stability and may be associated with intracranial aneurysms." (PMID 37737709, 2023). "They further suggest that mutations in COL22A1 could be one of the causes of intracranial aneurysms in humans." (PMID 30541770, 2018). "However, further genetic analysis using larger patient samples is needed to confirm the association of mutations in COL22A1 with intracranial aneurysms." (PMID 30541770, 2018). "Our results identify a novel role for Col22a1 in maintaining vascular stability and suggest that mutations in COL22A1 could be one of the causes of intracranial aneurysms." (PMID 30541770, 2018). "Mutations in COL22A1 are likely to be associated with intracranial aneurysms." (PMID 30541770, 2018). "In addition, COL22A1 mutation may be closely associated with the occurrence of intracranial aneurysms." (PMID 36544490, 2022). "To test whether COL22A1 is associated with vascular disease in humans, we analyzed data from a previous study that performed whole-exome sequencing of 45 individuals from seven families with intracranial aneurysms." (PMID 30541770, 2018). "Our finding that mmp9 could function downstream of col22a1 is consistent with the reported role of MMP9 in the formation of intracranial aneurysm in mice." (PMID 30541770, 2018).
muscular dystrophy (4 papers, 2021 to 2025). Muscular dystrophy (MD) refers to a group of more than 30 genetic diseases characterized by progressive weakness and degeneration of the skeletal muscles that control movement. "COL22A1 encodes the synthesis of collagen XXII; the knockout of COL22A1 in zebrafish resulted in a muscular dystrophy-like phenotype and exogenous COLXXII could rescue the defect." (PMID 40362156, 2025). "Knockdown of col22a1 in zebrafish induces a muscular dystrophy phenotype, supporting an essential role for this protein for muscle development and/or function in fishes." (PMID 40560263, 2025). "col22a1 knockdown has further been shown to induce muscular dystrophy and muscle fiber detachment in zebrafish embryos." (PMID 36462083, 2023). "Targeting of Col22a1 in Zebrafish morpholino models has led to the observation that these animals display muscular dystrophy most likely due to a severely disrupted myotendinous junction that could even lead to muscle detachment." (PMID 34831244, 2021).
aneurysm (3 papers, 2018 to 2022). Bulging or ballooning in an area of an artery secondary to arterial wall weakening. "In humans, COL22A1 genetic variants have been linked to a higher risk of aneurysms and are being investigated for their potential contribution to musculoskeletal soft tissue injuries." (PMID 36612834, 2022). "Future studies will be focused on defining how COL22A1 might mediate the formation of aneurysms." (PMID 30541770, 2018).
glioma (3 papers, 2023 to 2025). A benign or malignant brain and spinal cord tumor that arises from glial cells (astrocytes, oligodendrocytes, ependymal cells). "Recent evidence has pinpointed the potential role of COL22A1 in the tumorigenesis of gliomas and lung adenocarcinoma." (PMID 40438725, 2025). "Our study highlights the critical role of COL22A1 in gliomas and glioma-Induced Autoimmune Encephalitis, demonstrating its strong association with poor prognosis and its significant involvement in tumor immune regulation." (PMID 40114922, 2025). "A pro-oncogenic role for COL22A1, evidenced by impaired proliferation, migration, and invasion capacities, was evidenced upon shRNA-mediated COL22A1 silencing in glioma U87 and LN18 cells." (PMID 37737709, 2023). "We next focused on COL22A1, and verified its overexpression in both glioma cell lines and clinical samples." (PMID 37737709, 2023). "There is evidence suggesting the potential oncogenic role of COL22A1 in gliomas." (PMID 40438725, 2025). "Compared with NHAs, COL22A1, and IGF2BP2 mRNA levels were significantly increased in the glioma cell lines, while MPO levels were instead similar." (PMID 37737709, 2023).
Anxiety (2 papers, 2023 to 2025). Intense feelings of nervousness, tension, or panic often arise in response to interpersonal stresses. "The allele rs62522074-C has the highest OR of 1.66, implicating COL22A1, associated with collagen structure, in anxiety development." (PMID 40125487, 2025). "COL22A1 is crucial for connective tissue structure but has no direct anxiety associations; possible indirect influences on emotional health exist." (PMID 40125487, 2025). "Recent GWAS have also identified seven significant genetic loci—RNU6–168P, MAT2B, DKK2, DIP2C, COL22A1, OR4L1, and ATXN1—that influence anxiety traits in Caesarean-born offspring." (PMID 40125487, 2025).
breast carcinoma (2 papers, 2022). "Il7R and COL22A1 are related to the TME of lung cancer and breast cancer, respectively." (PMID 35813821, 2022).
glioblastoma (2 papers, 2025). The most malignant astrocytic tumor (WHO grade IV). "COL22A1 expression was higher in glioblastoma tissues and cell lines, and correlated with clinical factors such as higher age, WHO grade, and IDH mutation status." (PMID 40114922, 2025). "In this study, we identified COL22A1 as a novel shared biomarker in glioblastoma (GBM) and its induced autoimmune encephalitis (AE) through radiogenomics." (PMID 40114922, 2025).
hemorrhage (2 papers, 2018 to 2022). Loss of blood from the vascular compartment to the exterior or into nonvascular body space as a result of rupture or severance of the blood vessels. "Ton and colleagues studied a knockdown of a Col22a1 gene in zebrafish, finding a 2.5-fold increase in the number of cerebral hemorrhages compared to the wild type zebrafish, which they attributed to abnormal vessel wall permeability." (PMID 35052463, 2022). "We demonstrated that col22a1 homozygous mutant adults, but not their heterozygous siblings, exhibit increased frequency of hemorrhages." (PMID 30541770, 2018).
intracranial hemorrhage (2 papers, 2018 to 2021). Bleeding within the SKULL, including hemorrhages in the brain and the three membranes of MENINGES. "In a different Zebrafish study, genetic disruption of the Col22a1 gene has led to an increased risk of intracranial hemorrhages due to increased vascular permeability." (PMID 34831244, 2021). "Homozygous col22a1 mutant embryos show higher sensitivity to cardiovascular stress and increased vascular permeability, resulting in a greater percentage of embryos with intracranial hemorrhages." (PMID 30541770, 2018).
lung carcinoma (2 papers, 2017 to 2022). "COL22A1 has been identified as a recurrently mutated gene in lung cancer." (PMID 28099461, 2017).
lung fibrosis (2 papers, 2019 to 2025). "In conclusion, our findings suggest that the increased expression of COL22A1 is associated with the pathogenesis of fibrosis in SSc and that the regulation of COL22A1 expression may have important implications for skin fibrosis as well as lung fibrosis." (PMID 30678304, 2019).
nasopharyngeal carcinoma (2 papers, 2022 to 2025). A carcinoma arising from the nasopharyngeal epithelium. "COL22A1 has been previously demonstrated to promote the survival of nasopharyngeal carcinoma cells by abrogating cellular senescence." (PMID 40438725, 2025). "To get the downstream pathways of COL22A1, we established overexpression of COL22A1 nasopharyngeal carcinoma cells with the addition of the CDK4/6 inhibitor (Palbociclib)." (PMID 36196630, 2022). "We first obtained the differentially expressed gene EN1 by GEO data screening, and then down‐regulated EN1 in nasopharyngeal carcinoma cells followed by RNA sequencing revealed that the nasopharyngeal carcinoma cell cycle and the downstream gene COL22A1 were altered." (PMID 36196630, 2022). "To investigate how EN1 affects the nasopharyngeal carcinoma cell cycle, we verified the relationship between EN1 and COL22A1 using a dual luciferase reporter." (PMID 36196630, 2022).
Osteopenia (2 papers, 2021 to 2022). Osteopenia is a term to define bone density that is not normal but also not as low as osteoporosis. "Next, we applied cellular and dynamic histomorphometry to define the underlying cellular cause for the observed trabecular osteopenia in Col22a1-deficient mice." (PMID 34831244, 2021). "We observed that Col22a1-deficient mice display trabecular osteopenia, accompanied by significantly increased osteoclast numbers per bone surface." (PMID 34831244, 2021). "It has recently been shown that COL22A1 is involved in mice bone remodeling and is expressed in bone-forming osteoblasts, but not bone-resorbing osteoclasts—COL22A1-deficient mice displayed trabecular osteopenia as well as a significantly increased osteoclast number." (PMID 36612834, 2022). "Our data demonstrate that Col22a1-deficiency specifically causes trabecular osteopenia with an increased osteoclast number, which is not explained by a shifted Rankl/Opg ratio." (PMID 34831244, 2021).
squamous cell carcinoma (2 papers, 2020 to 2022). A carcinoma arising from squamous epithelial cells. "The upregulation of COL22A1 has been proposed as a useful prognostic predictor in patients with squamous cell carcinoma of the head and neck." (PMID 32858528, 2020).
brain tumors (1 paper, 2023). "Our current study, which focused exclusively on grade 4 diffuse gliomas, the most aggressive primary brain tumors, revealed that a nomogram based on COL22A1, IGFBP2, and MPO expression can reliably evaluate patient prognosis." (PMID 37737709, 2023).
developmental delay (1 paper, 2017). "COL22A1 and COL11A1 exhibit increased expression in the bone tissue and hippocampus of mice with some of the symptoms of Kleefstra Syndrome (developmental delay, hypotonia, and craniofacial abnormalities), which is often accompanied by autistic symptoms and intellectual disability in humans." (PMID 29045412, 2017).
fibroids (1 paper, 2025). "The most significant variant was rs56897532 (OR 0.78, 95% CI 0.72–0.85, p = 5.39 × 10−9) in COL22A1 (intergenic) and is a novel gene association with fibroids." (PMID 40050615, 2025).
fibrosis (1 paper, 2021). the formation of excess fibrous connective tissue in an organ or tissue in a reparative or reactive process. "Thus, E2 contributes to dermal fibrosis through inducing Col22A1." (PMID 33640015, 2021).
head and neck squamous cell carcinoma (1 paper, 2019). A squamous cell carcinoma that arises from any of the following anatomic sites: lip and oral cavity, nasal cavity, paranasal sinuses, pharynx, larynx, and salivary glands. "Transcript levels of COL22A1 are elevated in the head and neck squamous cell carcinoma (HNSCC) and are proposed as prognostic predictors for HNSCC." (PMID 30678304, 2019).
Hypertension (1 paper, 2018). The presence of chronic increased pressure in the systemic arterial system. "At present, we do not know whether hypertension was present in the COL22A1-overexpressing zebrafish embryos, but the documented phenotypes resemble typical features of IA." (PMID 30541770, 2018).
lung adenocarcinoma (1 paper, 2025). A carcinoma that arises from the lung and is characterized by the presence of malignant glandular epithelial cells. "Additionally, in the lung adenocarcinoma cohort from The Cancer Genome Atlas (TCGA) database, COL22A1 has been identified as a key predictor of prognosis in a well-crafted multivariate risk model." (PMID 40438725, 2025).
malignant glioma (1 paper, 2023). A grade III or grade IV glioma arising from the central nervous system. "Therefore, in this study we investigated this association through bioinformatics methods, constructed a risk model based on three angiogenesis-related genes differentially expressed in grade 4 diffuse gliomas, and demonstrated a pro-oncogenic role for COL22A1 in malignant glioma cells in vitro." (PMID 37737709, 2023).
osteosarcoma (1 paper, 2022). A usually aggressive malignant bone-forming mesenchymal neoplasm, predominantly affecting adolescents and young adults. "Therefore, our study indicates that the resting dendritic cell signature constructed by AOC3, CDK6, COL22A1, and RNASE6 may contribute to predicting osteosarcoma prognosis and thus therapy guidance." (PMID 36189307, 2022).
prostate carcinoma (1 paper, 2022). A carcinoma that arises from epithelial cells of the prostate gland. "COL22A1 is located at 8q24.2, where the most frequent gain has been reported in primary and advanced prostate cancer." (PMID 36230636, 2022).
tumor (13 papers, 2015 to 2025). "Like many in its family, COL22A1 and related collagen products are implicated in promoting tumor development, indicating its potential significance in cancer biology and tumor progression." (PMID 40114922, 2025). "Furthermore, the expression of COL22A1 is associated with common clinical risk factors such as older age, male gender, and higher tumor grade." (PMID 40114922, 2025). "As a scaffold protein involved in assembling the ECM, COL22A1, similar to other collagen genes, can impact various malignant characteristics in tumor cells." (PMID 40438725, 2025). "In a mouse xenograft model, COL22A1 suppression impeded tumor formation of GBM cells, which was confirmed by reduced Ki67 expression." (PMID 40438725, 2025). "Although an association between collagen COL22A1 expression and vascular stability has been reported, the oncogenic role of COL22A1 in relation to tumor angiogenesis remains uncertain." (PMID 37737709, 2023). "Mutations in other collagens, such as COL6A6, COL22A1, COL6A3, COL12A1, and COL14A1, were also noted in a variety of tumor types." (PMID 34584216, 2021). "Other predicted targets for hsa-miR-29c are BCL11A and COL22A1, involved in tumour formation, regulator of structural molecular activity and extracellular region." (PMID 32182819, 2020). "The fact that Collagen signatures exhibit strong predictive power may be because these members themselves (COL1A1, COL4A3, COL5A1, COL11A1, COL22A1) have been reported to predict tumor prognosis." (PMID 37476379, 2023). "Results demonstrated higher levels of COL22A1 in tumor specimens." (PMID 37737709, 2023). "Furthermore, a marked decrease in tumor weight was observed in the COL22A1-silenced group." (PMID 40438725, 2025). "However, it has not been reported whether the other four genes, NCAPG, S100A2, DERL3, and COL22A1, exert any biological role in the interaction between tumor and immune cells." (PMID 34136486, 2021). "Future research should focus on elucidating the precise mechanisms of COL22A1-mediated PI3K/AKT activation, exploring its therapeutic potential, and investigating its role in treatment resistance and tumor microenvironment modulation in GBM." (PMID 40438725, 2025). "Our findings reveal COL22A1 as a potential prognostic marker and therapeutic target in GBM, highlighting its role in promoting tumor aggression via the PI3K/AKT pathway." (PMID 40438725, 2025). "By demonstrating COL22A1's impact on GBM cell behavior through the PI3K/AKT pathway, this study provides novel mechanistic insights into how COL221A influence intracellular signaling to promote tumor progression." (PMID 40438725, 2025). "Secondly, the interaction between the tumor and its microenvironment is a complex process, and we did not explore the effects of COL22A1 on the GBM and AE TME at the single-cell level." (PMID 40114922, 2025). "In parallel, the scRNA data from 15 PDAC tissues samples also showed higher infiltration of cells expressing SMC/fibroblast markers (PDPN, COL5A1, COL22A1, TIMP3, SPARC, WT1, GFPT2) in samples with higher proportions/fractions of MUC16-expressing tumor (epithelial) cells (n = 7)." (PMID 36816942, 2023). "On the other hand, Col4a1, Col4a3, Col4a5, Col5a3, Col11a2, Col14a1, Col15a1, Col16a1, and Col22a1 were found in normal ECM but not in tumor ECM; Col25a1 was found only in tumor ECM but not in normal ECM." (PMID 36547361, 2022). "Future investigations into COL22A1's role in cellular senescence and immune modulation in GBM could further elucidate its multifaceted functions in cancer biology, building on existing knowledge from other tumor types." (PMID 40438725, 2025).
cancer (9 papers, 2018 to 2025). A tumor composed of atypical neoplastic, often pleomorphic cells that invade other tissues. "The consistent association of COL22A1 with poor prognosis across various cancers, including GBM, reinforces its potential as both a prognostic biomarker and a therapeutic target." (PMID 40438725, 2025). "Dysregulation of COL22A1 has been observed in various cancers, such as head and neck squamous cell carcinoma and breast cancer." (PMID 40438725, 2025). "Our findings on COL22A1 in GBM align with and extend previous observations in other cancer types, supporting a conserved oncogenic role for this ECM protein." (PMID 40438725, 2025). "We found that the mRNA expression of IL7R, COL22A1, ZNF185, and SRD5A2 were upregulated in cancer tissues, while PTGS2 and CLDN1 were higher in normal tissues, consistent with our previous analysis." (PMID 35813821, 2022).
COL22A1 also shares sentences with these, for which no sentence is quoted: melanoma (3 papers); lymph node metastasis (2); autoimmune encephalitis (1); breast tumors (1); colon cancer (1); gastric tumors (1); head and neck tumours (1); Hepatic fibrosis (1); Intellectual disability (1); Kleefstra syndrome (1); neurodegenerative disease (1); pituitary adenoma (1); pituitary tumor (1); scoliosis (1); Sepsis (1); systemic sclerosis (1).